RNY1P2 (RNY1 pseudogene 2)
Gene: Miscellaneous RNA gene on chromosome 13 (102,016,953 to 102,017,069, reverse strand). Ensembl gene ENSG00000201690.
Homologues: Orthologues: chimpanzee Y_RNA (99% identical). Paralogues in human: Y_RNA (84% identical), Y_RNA (81% identical), RNY1 (80% identical), Y_RNA (79% identical), Y_RNA (78% identical), Y_RNA (77% identical), RNY1P5 (76% identical), Y_RNA (76% identical), Y_RNA (75% identical), Y_RNA (74% identical), RNY1P11 (73% identical), Y_RNA (73% identical), and 90 more.